ADGRG6 (adhesion G protein-coupled receptor G6)
Description:
Adhesion G protein-coupled receptor (aGPCR) for steroid hormones, such as progesterone and 17alpha-hydroxyprogesterone (17OHP). Involved in many biological processes, such as myelination, sprouting angiogenesis, placenta, ear and cartilage development (By similarity). Ligand binding causes a conformation change that triggers signaling via guanine nucleotide-binding proteins (G proteins) and modulates the activity of downstream effectors, such as adenylate cyclase. ADGRG6 is coupled to G(i) G alpha proteins and mediates inhibition of adenylate cyclase. Also able to couple to G(q) G proteins. Involved in myelination of the peripheral nervous system: required for differentiation of promyelinating Schwann cells and for normal myelination of axons. Also acts as a regulator of body length and bone mass. Acts as a regulator of blood-brain barrier formation in the central nervous system vie its association with LRP1 and ITGB1 (By similarity).
Synonyms: DREG; GPR126; VIGR; FLJ14937; APG1; LCCS9; PR126; PS1TP2
Tractability: Antibody: UniProt places it where antibodies can reach, with high confidence; its Gene Ontology location is reachable by antibodies, with high confidence; UniProt predicts a signal peptide or a membrane-spanning region. PROTAC: ubiquitination databases record sites on it.
Target class: Family B G protein-coupled receptor; Membrane receptor
Gene: Protein-coding gene on chromosome 6 (142,301,854 to 142,446,266, forward strand). Ensembl gene ENSG00000112414.
Subcellular location: Cell membrane
Pathways (Reactome):
Developmental Biology: EGR2 and SOX10-mediated initiation of Schwann cell myelination
Gene Ontology:
Molecular function: G protein-coupled receptor activity; collagen binding; endopeptidase activity; extracellular matrix binding; laminin binding; transmembrane signaling receptor activity
Biological process: adenylate cyclase-inhibiting G protein-coupled receptor signaling pathway; myelination; Schwann cell differentiation; adenylate cyclase-activating G protein-coupled receptor signaling pathway; adenylate cyclase-modulating G protein-coupled receptor signaling pathway; cartilage development; cell surface receptor signaling pathway; establishment of blood-brain barrier; G protein-coupled receptor signaling pathway; heart trabecula formation; myelination in peripheral nervous system; nervous system development; placenta development; regulation of bone mineralization; regulation of sprouting angiogenesis
Cellular component: cell surface; cytoplasm; plasma membrane; endoplasmic reticulum membrane; membrane
Genetic constraint (gnomAD): Loss-of-function variants: 18 observed, 42.4 expected, observed/expected ratio (o/e) 0.42, 90% interval 0.29 to 0.63. The upper end of that interval is the gene's LOEUF score, 0.63, which puts it in group 2 of 6, group 1 being the genes least tolerant of losing a copy. Missense variants: 557 observed, 617.88 expected, observed/expected ratio (o/e) 0.9, 90% interval 0.84 to 0.97. Synonymous variants: 215 observed, 230.4 expected, observed/expected ratio (o/e) 0.93, 90% interval 0.83 to 1.04.
Homologues: Orthologues: chimpanzee ADGRG6 (99% identical), macaque ADGRG6 (98% identical), rabbit ADGRG6 (90% identical), dog ADGRG6 (89% identical), pig ADGRG6 (88% identical), mouse Adgrg6 (82% identical), guinea pig ADGRG6 (81% identical), rat Adgrg6 (80% identical), tropical clawed frog adgrg6 (54% identical), zebrafish adgrg6 (50% identical). Paralogues in human: ADGRG4 (31% identical), ADGRG2 (29% identical), ADGRL2 (16% identical), ADGRL3 (16% identical), ADGRF5 (15% identical), ADGRL1 (15% identical), ADGRB2 (14% identical), ADGRA3 (13% identical), ADGRA2 (13% identical), ADGRB1 (13% identical), ADGRD2 (13% identical), ADGRE2 (12% identical), and 30 more.
Diseases named in the same sentence as ADGRG6 in open-access papers:
ADGRG6 is named in the same sentence as 79 diseases in open-access papers, as found by Europe PMC text mining. Sharing a sentence is not in itself a finding about the gene and the disease. The quoted sentences say what the papers report.
scoliosis (12 papers, 2016 to 2026). A congenital or acquired spinal deformity characterized by lateral curvature of the spine. "By cartilage-specific conditional ablation of Adgrg6 during embryonic development, we showed a mild increase in the susceptibility to scoliosis in mouse." (PMID 34318745, 2021). "Genome-wide association studies and subsequent meta-analysis of multiethnic AIS cohorts strongly implicate the ADGRG6 gene for susceptibility to scoliosis." (PMID 34318745, 2021). "Altogether, this suggested that loss of Adgrg6 in committed cartilages of the axial skeletal is sufficient to generate a mild susceptibility to scoliosis, although with a much lower penetrance compared with removal of Adgrg6 in the whole spine (i.e., Col2a1-Cre; Adgrg6f/f)." (PMID 34318745, 2021). "Conditional loss of Adgrg6 in multipotent osteochondral progenitors -giving rise to bone, cartilage, and some connective tissues- of the spine generated postnatal-onset scoliosis, ribcage deformity, and increased incidence of midline clefts in the endplates and annulus fibrosus." (PMID 31652254, 2019). "The first noted model of idiopathic-like scoliosis was a tissue-specific knockout of adhesion G protein-coupled receptor G6 (Adgrg6; previously known as Gpr126), orthologous to a gene linked to human AIS." (PMID 40888060, 2025). "Progressive scoliosis, albeit to a lesser extent, was also observed when Adgrg6 was deleted from committed chondrocytes (using ATC:Cre)." (PMID 38277211, 2024). "In mouse, conditional deletion of Adgrg6 in skeletal cartilage (using Col2a1-Cre) produces a progressive scoliosis of the thoracic spine during postnatal development that is marked by herniations within the cartilaginous endplates of involved vertebrae." (PMID 38277211, 2024). "Therefore, our observations suggest that embryonic deletion of Adgrg6 leads to subtle structural or biomechanical changes of these structural elements of the spine, which in turn may lead to increased susceptibility of scoliosis during periods of rapid skeletal growth." (PMID 34318745, 2021). "Ablation of Adgrg6 in dense connective tissues leads to late-onset scoliosis and compromised biomechanical properties of the tendons." (PMID 34318745, 2021). "Longitudinal X-ray analyses demonstrated that both embryonic and perinatal ablation of Adgrg6 in committed cartilage tissues of the axial skeleton led to moderate to low penetrance of scoliosis in ATC; Adgrg6f/f mice." (PMID 34318745, 2021). "Here, we showed that ablation of Adgrg6 in the IVD during embryonic development increased the penetrance of scoliosis in mice." (PMID 34318745, 2021). "Since the development of scoliosis is often linked with IVD deformity, we sought to investigate the role of Adgrg6 specifically in cartilaginous tissues of the IVD during embryonic and postnatal development." (PMID 31652254, 2019). "We previously demonstrated a critical role for Adgrg6 in the formation of scoliosis in young mice (onset at around P20-P40)." (PMID 31652254, 2019). "In previous studies we demonstrated a clear role for Adgrg6 in the formation of late-onset scoliosis in mouse, however the cellular pathogenesis of this process remained unresolved." (PMID 31652254, 2019). "Additional ongoing studies are seeking understand the cellular pathogenesis underlying Adgrg6-dependent scoliosis and how spine curvature is related to molecular changes in the CEP and growth plate Adgrg6 mutant mice." (PMID 31652254, 2019). "The heritability of scoliosis is not likely explained solely by variants in the ADGRG6 locus as most variants only explain between 1 and 2% of heritability given the published odd ratios each variant." (PMID 34318745, 2021). "Ablation of Adgrg6 in cartilaginous tissues leads to scoliosis in the mouse." (PMID 34318745, 2021).
scoliosis (continued). "Here, we show that Scx-Cre; Adgrg6f/f mice exhibit reduced elastic moduli in the tendon fascicles of the tail, suggesting that scoliosis in these Adgrg6 mutant mouse models of AIS is primarily driven by biomechanical instability of the paraspinal tendons and ligaments." (PMID 34318745, 2021). "Scoliosis is a common phenotype in mutant mouse models that disrupt genes involved with the development and homeostasis of cartilages and connective tissues, including Adgrg6/Gpr126, Sox9, Shp2 (Ptpn11), Gdf5/6 and Fgf3." (PMID 31848143, 2019). "Interestingly, increased midline clefts were observed in conditional Adgrg6/Gpr126 scoliosis mutant mice." (PMID 31848143, 2019). "However, conditional ablation of Adgrg6 in osteochondral progenitor cells generated a reproducible genetic mouse model that displayed postnatal-onset scoliosis without causing obvious patterning defects of the vertebral column." (PMID 34318745, 2021). "However, we observed no significant changes in GAG quantity or alterations in specific GAG species, demonstrating that loss of Adgrg6 did not alter the expression of a significant class of proteoglycan species in the IVD at the initiation of scoliosis." (PMID 34318745, 2021). "Ablation of Adgrg6 during embryonic development resulted in 25% (n = 16) and 16.7% (n = 12) of ATC; Adgrg6f/f mice showing scoliosis at P20 and P180, respectively." (PMID 34318745, 2021). "As ADGRG6 is a key gene involved in human AIS, these findings open up novel therapeutic opportunities for human scoliosis." (PMID 34318745, 2021). "Next, we demonstrate that alterations in Adgrg6 signaling, in part through cAMP/CREB signaling, specifically in dense connective tissues, with a minor contribution from the cartilaginous tissues of the IVD, are key drivers of scoliosis." (PMID 34318745, 2021). "However, we showed a slight increase in the incidence of scoliosis in the ATC; Adgrg6f/f mice with embryonic deletion of Adgrg6 compared to perinatal deletion." (PMID 34318745, 2021). "Conditional knock‐out of Adgrg6 in osteoblasts did not result in scoliosis; instead, mutant mice showed delayed ossification and reduced growth, supporting a role for ADGRG6 in influencing body length." (PMID 33735533, 2021). "In contrast to the deletion of Adgrg6 in osteoblasts, deletion of Adgrg6 in chondrocyte lineages of the spine in mice resulted in abnormalities of the intervertebral disc (IVD), including mechanical stiffening and eventual disc herniation, or scoliosis, depending on the transgenic driver used." (PMID 33735533, 2021). "Further studies in which Adgrg6 was removed from various tissues of the spine (using specific Cre drivers) showed that dense connective tissues including ligaments and parts of the IVD, but not bone, mediate scoliosis in this model." (PMID 40888060, 2025).
adolescent idiopathic scoliosis (11 papers, 2016 to 2025). A scoliosis with no known cause arising in adolescent. "Mutations in ADGRG6 are factors in some musculoskeletal disorders, including adolescent idiopathic scoliosis, pectus excavatum, arthrogryposis multiplex congenita, and periodontitis." (PMID 39935605, 2025). "Loss of Adgrg6 in mature osteoblast lineages is dispensable of adolescent idiopathic scoliosis (AIS) development." (PMID 34318745, 2021). "The role of Adgrg6 in myelination and remyelination suggests that it could be a promising therapeutic target for peripheral demyelinating diseases and possibly other diseases linked to Adgrg6 malfunction, such as adolescent idiopathic scoliosis." (PMID 33180885, 2020). "Ablation of Adgrg6 in osteochondral progenitor cells models progressive adolescent idiopathic scoliosis (AIS) in mouse." (PMID 34318745, 2021).
bladder cancer (10 papers, 2019 to 2025). "For instance, ADGRG6 promotes breast cancer growth upon progesterone stimulation, serves as a mutation marker for bladder cancer recurrence and immunotherapy monitoring, and drives colorectal cancer proliferation via HDAC2 and GLI2 signaling." (PMID 41614755, 2025). "Abnormal expression and potential role of ADGRG6 were recently implicated in several cancers, including colon, breast, and bladder cancers." (PMID 40226617, 2025). "Therefore, the high mutation rate of ADGRG6 enhancer hotspot mutations in bladder cancer patients in this study was attributed to the high sensitivity of the ARMS‐qPCR assay and the fact that urine allows for the better tumor information collection." (PMID 37081791, 2023). "We here present a novel urine test for ADGRG6 hotspot mutations with high accuracy and sensitivity, which may potentially serve as a rapid and non‐invasive tool for bladder cancer early screening and follow‐up relapse monitoring." (PMID 37081791, 2023). "In bladder cancer, recurrent ADGRG6 enhancer hotspot mutations (chr." (PMID 37081791, 2023). "So the ADGRG6 hotspot mutations may be a good clinical biomarker candidate to diagnosis in bladder cancer." (PMID 37081791, 2023). "In this study, the amplification refractory mutation system combined with quantitative real‐time PCR (ARMS‐qPCR) method was developed to rapidly and sensitively detect the specific mutations of ADGRG6 enhancer providing a flexible and easy way to screen bladder cancer." (PMID 37081791, 2023). "Indeed, recent work has focused on these twin hotspots mutations in PLEKHS1 and ADGRG6 (also called GPR126) as potential drivers or biomarkers of bladder cancer." (PMID 33707442, 2021). "While ADGRG6 has been extensively studied in neurodevelopment, its role in cancer is documented in colon, breast, and bladder cancers compared to its unexplored role in PAAD." (PMID 40226617, 2025). "Mutations at specific hotspots in non-coding regions of ADGRG6, PLEKHS1, WDR74, TBC1D12 and LEPROTL1 frequently occur in bladder cancer (BC)." (PMID 36658180, 2023). "Of interest, whole-genome sequencing has identified ADGRG6 enhancer mutations and FRS2 duplications as angiogenesis-related drivers in bladder cancer." (PMID 35213989, 2022). "Functional assays have demonstrated that depletion of ADGRG6 or FRS2 expression in bladder cancer cells compromises their abilities to recruit endothelial cells and induce tube formation." (PMID 35213989, 2022). "ADGRG6 plays an important role in bladder cancer incidence and development." (PMID 37081791, 2023).
arthrogryposis multiplex congenita (5 papers, 2017 to 2025). Arthrogryposis multiplex congenita (AMC) is a group of disorders characterized by congenital limb contractures. "Probands from three consanguineous families with Lethal Congenital Contracture Syndrome 9 (LCCS9), a rare form of Severe Arthrogryposis Multiplex Congenita (AMC), were found to harbor different homozygous recessive mutations in the ADGRG6 coding sequence." (PMID 33735533, 2021). "In humans, a missense substitution of ADGRG6 impairs autoproteolysis of the receptor, which results in severe arthrogryposis multiplex congenita." (PMID 39935605, 2025). "In contrast, homozygosity for a mutation that severely reduces the auto-proteolytic function of ADGRG6 has been shown in severe arthrogryposis multiplex congenita." (PMID 29240829, 2017).
idiopathic scoliosis (5 papers, 2015 to 2023). A scoliosis with no known cause. "This is mirrored by the situation in ADGRG6 (also called GPR126), a gene previously associated to idiopathic scoliosis." (PMID 29240829, 2017). "This further argues for the importance of the GAIN domains and supports our idea that any mutations abolishing their function (in ADGRG6 or CELSR2) would likely lead to more severe phenotypes than idiopathic scoliosis." (PMID 29240829, 2017). "ADGRG6 is also connected with the reduced body mass index and its activity/function seems to be correlated with osteoblast metabolism and bone calcification (both altered in idiopathic scoliosis)." (PMID 30598481, 2019). "The ADGRG6 variants that have been associated to idiopathic scoliosis have been intronic, and presumably only mildly or not directly functional." (PMID 29240829, 2017).
pancreatic cancer (4 papers, 2022 to 2026). "By integrating bioinformatic, experimental, and clinical evidence, this study expands the current understanding of ADGRG6 biology in pancreatic cancer and provides a conceptual framework for exploring ADGRG6 as a therapeutic target in future precision oncology and immunomodulation studies." (PMID 41614755, 2025). "To assess the impact of ADGRG6 knockdown on the growth of subcutaneously transplanted pancreatic tumors in a mouse model, we injected BALB/c nude mice with either control or ADGRG6 knockdown CFPAC-1 cells (1 × 106 cells per mouse)." (PMID 40226617, 2025). "To examine ADGRG6’s functional role in PAAD cellular proliferation, migration, and invasion processes, we conducted targeted silencing of ADGRG6 mRNA in AsPC-1 and BxPC-3 pancreatic cancer cell lines through specific siRNAs (si-ADGRG6), utilizing si-NC as negative control." (PMID 41614755, 2025).
periodontitis (4 papers, 2016 to 2025). An acute or chronic inflammatory process that affects the tissues that surround and support the teeth. "Furthermore, in the Japanese population, the ADGRG6 single nucleotide polymorphism rs536714306 may have an association with aggressive periodontitis." (PMID 39935605, 2025).
urothelial bladder carcinoma (4 papers, 2020 to 2023). "ADGRG6 is a member of the adhesion G protein-coupled receptor family and the depletion of ADGRG6 expression in urothelial bladder carcinoma cells compromised their ability to recruit endothelial cells and induce tube formation." (PMID 33986766, 2021).
acute myeloid leukemia (1 paper, 2021). Acute myeloid leukemia (AML) is a group of neoplasms arising from precursor cells committed to the myeloid cell-line differentiation. "A transcriptomic analysis of 772 GPCRs in 148 acute myeloid leukemia (AML) samples, encompassing different subgroups, identified ADGRG6 as one of 19 down‐regulated GPCRs, with others including the closely related ADGRG1 and SMO." (PMID 33735533, 2021).
arthrogryposis (1 paper, 2019). A rare, non-progressive congenital disorder characterized by multiple joint contractures which are present at birth. "Homozygote loss of function mutations in ADGRG6 were found to be associated with lethal arthrogryposis." (PMID 30598481, 2019).
depression (1 paper, 2024). "Finally, the gene ADGRG6, which was identified by the alcohol consumption network, has been associated with depression and smoking initiation." (PMID 38464225, 2024).
disc degeneration (1 paper, 2019). "We establish ADGRG6 and STAT3 as novel regulators of endplate integrity of the intervertebral disc in mouse and suggest that modulation of ADGRG6/STAT3 signaling could provide robust disease-modifying targets for endplate-oriented disc degeneration in humans." (PMID 31652254, 2019). "Taken together, our work establishes Adgrg6 as a novel regulator of IVD endplate and growth plate integrity in the mouse and suggests that modulation of ADGRG6/STAT3 signaling could provide robust disease-modifying targets for endplate-oriented disc degeneration, in humans." (PMID 31652254, 2019).
kidney cancer (1 paper, 2025). Primary or metastatic malignant neoplasm involving the kidney. "Additionally, CPTAC data showed that ADGRG6 protein expression was higher in tumors compared to normal tissues in KC (kidney cancer) and PDAC (pancreatic ductal adenocarcinomas)." (PMID 40226617, 2025).
lung carcinoma (1 paper, 2020). "Additionally, a novel ROS1-ADGRG6 rearrangement induced by the fusion of exons 1–33 of ROS1 on chr6 to exons of 2–26 of ADGRG6 on chr6 has been previously reported in lung cancer." (PMID 32322582, 2020).
nematode infection (1 paper, 2021). "Taste receptor TAS2R16, adhesion receptor ADGRG6 (GPR126) and orphan receptor GPRC5C were enriched in abomasal tuft cells, and our data suggest these may be the main receptors involved in sensing nematode infection in the abomasum." (PMID 34880874, 2021).